RBM12 (RNA binding motif protein 12)
Synonyms: SWAN; KIAA0765; HRIHFB2091; SCZD19
Tractability: Small molecule: it has a high-quality binding pocket. PROTAC: ubiquitination databases record sites on it; its protein half-life has been measured.
Gene: Protein-coding gene on chromosome 20 (35,648,925 to 35,664,956, reverse strand). Ensembl gene ENSG00000244462.
Subcellular location: Nucleus
Subcellular location (Human Protein Atlas): Nucleoplasm
Gene Ontology:
Molecular function: protein binding; RNA binding; nucleic acid binding
Biological process: regulation of RNA splicing
Cellular component: nucleoplasm; ribonucleoprotein complex; nucleus
Genetic constraint (gnomAD): Loss-of-function variants: 24 observed, 38.71 expected, observed/expected ratio (o/e) 0.62, 90% interval 0.45 to 0.87. The upper end of that interval is the gene's LOEUF score, 0.87, which puts it in group 3 of 6, group 1 being the genes least tolerant of losing a copy. Missense variants: 1,061 observed, 1,246.3 expected, observed/expected ratio (o/e) 0.85, 90% interval 0.81 to 0.9. Synonymous variants: 420 observed, 449.24 expected, observed/expected ratio (o/e) 0.93, 90% interval 0.86 to 1.01.
Homologues: Orthologues: chimpanzee RBM12 (100% identical), macaque CPNE1 (99% identical), pig RBM12 (95% identical), dog RBM12 (95% identical), guinea pig RBM12 (95% identical), rat Rbm12 (91% identical), tropical clawed frog rbm12 (62% identical), zebrafish rbm12 (54% identical), Caenorhabditis elegans rbm-12 (18% identical), Caenorhabditis elegans hrpf-2 (10% identical), Drosophila melanogaster fus (10% identical), Drosophila melanogaster glo (10% identical), and 1 more. Paralogues in human: RBM12B (30% identical), ESRP2 (10% identical), ESRP1 (10% identical), HNRNPH2 (10% identical), HNRNPH1 (10% identical), HNRNPF (9% identical), GRSF1 (8% identical), HNRNPH3 (8% identical).
Diseases named in the same sentence as RBM12 in open-access papers:
RBM12 is named in the same sentence as 15 diseases in open-access papers, as found by Europe PMC text mining. Sharing a sentence is not in itself a finding about the gene and the disease. The quoted sentences say what the papers report.
psychosis (6 papers, 2017 to 2025). "Although mutations in RBM12 have been linked to heritable psychosis and neurodevelopmental defects, its precise cellular functions are not well-understood." (PMID 37543364, 2023). "In terms of physiology, RBM12 was recently discovered as a high-penetrance risk factor for familial schizophrenia and psychosis in a family-based whole-genome study to identify rare coding sequence variants associated with disease segregation in a pedigree." (PMID 37543364, 2023). "RBM12 is a high-penetrance risk factor for familial schizophrenia and psychosis, yet its precise cellular functions and the pathways to which it belongs are not known." (PMID 37543364, 2023). "However, one report demonstrated that a truncating variant of RBM12 is associated with psychosis, which remains to be a possible relation between the RBM12 variant and the phenotype of the patient." (PMID 36619507, 2022). "Another would be to search for affected relatives of subjects with candidate variants in order to see if the variants cosegregate with disease, a strategy which was successful in implicating RBM12 in the aetiology of psychosis." (PMID 29564678, 2018).
type 2 diabetes (2 papers, 2021 to 2025). "Consistent with effects of damaging variants in HTRA1, SGTB, and RBM12 acting independently of traditional cardiovascular risk factors, these associations persisted after adjusting for LDL cholesterol, smoking, type 2 diabetes, body mass index, and systolic blood pressure." (PMID 41190437, 2025).
breast carcinoma (1 paper, 2022). "Seven genes were shared between prostate and positive breast cancer responders (TRNT1, NUFIP1, TDG, HSPA8, OTUD6B, RBM12, and DENND3)." (PMID 35520391, 2022).
colorectal cancer (1 paper, 2019). A primary or metastatic malignant neoplasm that affects the colon or rectum. "The most significantly associated gene in this study, RBM12 is associated with colorectal cancer and tumorigenesis of Meibomian cell carcinoma." (PMID 31338326, 2019).
endometrial cancer (1 paper, 2019). Primary or metastatic malignant neoplasm involving the endometrium (mucous membrane that lines the endometrial cavity). "Seven genes, including RBM12, NDUFB6, ATP6V1A, RECK, SLC35E1, RFX3 (Bonferroni-corrected P < 0.05) and ATP8A1 (suggestive P < 10−5), and one long non-coding RNA, DLGAP4-AS1 (Bonferroni-corrected P < 0.05), were associated with endometrial cancer." (PMID 31338326, 2019).
epilepsy (1 paper, 2022). A brain disorder characterized by episodes of abnormally increased neuronal discharge resulting in transient episodes of sensory or motor neurological dysfunction, or psychic dysfunction. "For example, a frameshift variant of RBM12 was detected in a patient with epilepsy and mildly delayed development." (PMID 36619507, 2022).
peripheral vascular disease (1 paper, 2025). Any disorder affecting blood flow through the veins or arteries outside of the heart. "Loss-of-function variants in the RNA-binding protein RBM12 increased the risk of coronary, cerebrovascular, and peripheral vascular diseases to a similar extent." (PMID 41190437, 2025).
schizophrenia (1 paper, 2020). A major psychotic disorder characterized by abnormalities in the perception or expression of reality.
cancer (4 papers, 2008 to 2025). A tumor composed of atypical neoplastic, often pleomorphic cells that invade other tissues. "RBM12 was detected as upregulated in Meibomian cell carcinoma, a malignant tumour of themeibomian glands located in the eyelids." (PMID 18831769, 2008). "In summary, we analyzed and integrated data from 488 COAD and 155 READ patients, 102 cancer cell lines, more than 15,000 immunostainings, and ∼10,000 raw associations between RBPs and cancer genes to unravel new RBPs involved in COAD (NOP56, NAT10, RBM12, and FKBP1A) and READ (EMG1 and CSE1L)." (PMID 37384253, 2023). "Three variants in RBM12, one variant in NDUFB6, ten variants in DLGAP4-AS1, five variants in ATPV1A, eleven variants in RECK, four variants in SLC35E1, eight variants in RFX3, and eight variants in ATP8A1 were known somatically acquired mutations in various cancers." (PMID 31338326, 2019). "Intersecting the sets of pan-cancer compensated and toxic genes yields nine high-confidence ARGOS genes, six of which are also frequently amplified: RBM12, RBM14, SNRPA, ZBTB14, POU2F1, and CDKN1A." (PMID 39870664, 2025). "To highlight their relevance in cancer, we interrogated the HumanNet v3 and found that NOP56, RBM12, FKBP1A and EMG1 are highly interconnected with cancer genes and other RBPs, showing their potential to form tumorigenic RNA-regulons." (PMID 37384253, 2023). "Also, we were able to retrieve two other RBPs (RBM12 and FKBP1A) that were not essential for tumor cell survival, but they could be implicated in any other hallmark of cancer." (PMID 37384253, 2023).
tumor (3 papers, 2008 to 2023). "Our data indicate that, besides CD73, GALC transduction induces an increase in the levels of the importin karyopherin subunit alpha 4, kynureninase, and RNA-binding motif protein 12, all involved in tumor immune escape." (PMID 37445731, 2023).
cardiovascular disease (1 paper, 2025). "While RBM12 was not differentially regulated in the aorta from patients with cardiovascular disease, SGTB was significantly downregulated (false discovery rate–corrected P=2.1×10−5)." (PMID 41190437, 2025).
RBM12 also shares sentences with these, for which no sentence is quoted: atherosclerosis (1 paper); diabetes (1); melanoma (1); psychiatric disease (1).